HMGB1 (high mobility group box 1)
Diseases named in the same sentence as HMGB1 in open-access papers (continued):
Sharing a sentence is not in itself a finding about the gene and the disease.
renal dysfunction (4 papers, 2010 to 2024). "Existing paradigm of studies show that HMGB1 is central to the onset and progression of renal dysfunctions." (PMID 39840112, 2024). "Studies over the years outline a strong correlation between HMGB1 and pathogenesis of renal dysfunctions." (PMID 39682695, 2024). "Further adjustments for differences in markers of low-grade inflammation, endothelial and renal dysfunction and arterial stiffness did not attenuate these associations because plasma levels of HMGB1 were not independently associated with these variables." (PMID 22752054, 2012). "The adverse associations between HMGB1 and study outcomes were not appreciably attenuated after further adjustments for markers of LGI, endothelial and renal dysfunction and PP (models 6a–d), because HMGB1 was not independently associated with these variables." (PMID 22752054, 2012).
sickle cell disease (4 papers, 2021 to 2024). Sickle cell anemias are chronic hemolytic diseases that may induce three types of acute accidents: severe anemia, severe bacterial infections, and ischemic vasoocclusive accidents (VOA) caused by sickle-shaped red blood cells obstructing small blood vessels and capillaries. "HMGB1 increases platelet surface P2Y12 and promotes platelet ADP release, thereby enhancing ADP-mediated platelet activation in healthy subjects and individuals with sickle cell disease." (PMID 38456510, 2024).
skin tumors (4 papers, 2013 to 2025). "We conclude that HMGB1 is upregulated in wound-associated mouse and human skin tumours and that HMGB1 levels are regulated by leukocytic TLR-5 signalling." (PMID 25575023, 2015). "We therefore investigated HMGB1 as a candidate biomarker linking human and mouse wound-associated skin cancer." (PMID 25575023, 2015). "The results showed that HMGB1 plays a crucial role in the pathogenesis of skin cancer, prognosis, and therapeutical response to therapy." (PMID 36012593, 2022). "Indeed, evidence has highlighted that UV radiation stimulates HMGB1 release in keratinocytes in vitro and HMGB1 is expressed in skin tumors after chronic radiation." (PMID 40507265, 2025).
thrombotic disorders (4 papers, 2022 to 2025). "Circulating nucleic acids (CNAs), high-mobility group box 1 (HMGB1), von Willebrand factor (vWF), and S100b protein are notable markers of SI, indicative of tissue damage and implicated in thrombotic disorders." (PMID 41311551, 2025). "Furthermore, we critically evaluate therapeutic strategies targeting HMGB1 developed over the past decade, while proposing future directions for dual-target interventions that simultaneously modulate HMGB1 and platelet activity to combat inflammation-driven thrombotic disorders." (PMID 40514022, 2025). "This SI is driven by factors like circulating nucleic acids (CNAs), S100b, high-mobility group box 1 (HMGB1), and von Willebrand factor (vWF), which reflect tissue damage and contribute to thrombotic disorders, including the formation of blood clots." (PMID 41311551, 2025).
viral hepatitis (4 papers, 2019 to 2023). An acute or chronic inflammation of the liver parenchyma caused by viruses. "By suppressing high mobility group protein box 1 (HMGB1) cytokine activity and causing TLR4 gene deficit, 18βGA therapy reduced hepatic inflammatory damage in viral hepatitis." (PMID 36903944, 2023). "They found that treatment with GA inhibited hepatic inflammatory activity by blocking the high mobility group box-1 (HMGB-1) cytokine activity, suggesting a new therapy for acute viral hepatitis." (PMID 34961070, 2021).
acute monocytic leukemia (3 papers, 2012 to 2024). Acute monoblastic leukemia (AML-M5), is one of the most common subtypes of acute myeloid leukemia (AML) that is either comprised of more than 80% of monoblasts (AML-M5a) or 30-80% monoblasts with (pro)monocytic differentiation (AML-M5b). "The impact of the aptamers on the biological activity of HMGB1 was tested in the human acute monocytic leukemia cell line, THP-1." (PMID 39830661, 2024). "This study reported that ligand-activated PPAR-γ inhibited HMGB1 expression through upregulation of miR-142-3p and suppressed inflammatory response in human acute monocytic leukemia THP-1 cell line." (PMID 27563308, 2016). "We measured the concentration of TNF-α released by human acute monocytic leukemia cells (THP-1) in the presence of rLj-HMGB1." (PMID 22563397, 2012). "We further revealed that Lj-HMGB1 was able to induce the production of tumor necrosis factor-α (TNF-α), a pro-inflammatory mediator, in activated human acute monocytic leukemia cells." (PMID 22563397, 2012).
AIDS (3 papers, 2008 to 2022). A syndrome resulting from the acquired deficiency of cellular immunity caused by the human immunodeficiency virus (HIV). "This was in turn observed to inhibit pro-inflammatory mediator high-mobility group box-1 (HMGB1) expression, which is normally found to be increased in AIDs." (PMID 36291082, 2022).
airway hyperresponsiveness (3 papers, 2014 to 2025). "The anti-HMGB1 antibody animals exhibited diminished levels of IgE, inflammatory cytokines and inflammatory cell accumulation, airway hyperresponsiveness (AHR), mucus generation, smooth muscle thickness and lung collagen levels." (PMID 28630596, 2017). "As some studies have shown that Th17 cells mediate neutrophilic airway inflammation and airway hyperresponsiveness in mice; therefore, we postulated that induction of Th17 polarization by HMGB1 might represent a critical initiating event that results in neutrophilic airway inflammation and AHR." (PMID 24959003, 2014).
alcoholic steatohepatitis (3 papers, 2019 to 2022). "HMGB1 expression and translocation from the nucleus to the cytoplasm in human liver tissue from alcohol steatohepatitis patients was increased compared to healthy controls and correlated to disease severity." (PMID 33207634, 2020). "Using a transgenic mouse with HMGB1 knocked down mainly in hepatocytes, this study also demonstrated that lack of HMGB1 protects from alcoholic fatty liver diseases." (PMID 33207634, 2020). "Moreover, in chronic liver diseases, such as long-term hepatitis B virus (HBV) or hepatitis C virus (HCV) infection, primary biliary cirrhosis (PBC), or alcoholic steatohepatitis (ASH), the level of HMGB1 expression is correlated with the fibrosis stage." (PMID 31731454, 2019).
allergic contact dermatitis (3 papers, 2015 to 2024). An inflammatory skin condition caused by an immune response to direct contact between the skin and an allergen. "Our previous study suggested that necroptosis-mediated High mobility group box 1 (HMGB1) release from keratinocytes facilitates the progression of allergic contact dermatitis." (PMID 38429278, 2024). "Lastly, we evaluated the therapeutic effect of intravenous HMGB1 administration in a mouse model of allergic contact dermatitis (ACD), one of the most common inflammatory skin diseases." (PMID 26046579, 2015). "Finally, we showed the therapeutic activity of the HMGB1/BM-PDGFRα+ mesenchymal cell axis in an allergic contact dermatitis model." (PMID 26046579, 2015).
angina (3 papers, 2013 to 2025). "Secondary outcomes are cTnT, NT-proBNP, inflammatory/endothelial biomarkers (hs-CRP, IL-6, MMP-9, VEGF, HMGB1), and angina-related parameters (attack frequency, symptom severity)." (PMID 41195123, 2025). "Hashimoto and colleagues found similar results in a cohort of patients with unstable angina and non-ST-segment elevation myocardial infarction (NSTEMI), suggesting an association between higher HMGB-1 levels and risk of cardiovascular death." (PMID 36244983, 2022).
ankylosing spondylitis (3 papers, 2016 to 2021). An autoimmune chronic inflammatory disorder characterized by inflammation in the vertebral joints of the spine and sacroiliac joints. "In adult patients with ankylosing spondylitis, serum HMGB1 was significantly higher and could reflect the disease activity." (PMID 34247641, 2021).
arteriosclerosis (3 papers, 2018 to 2020). A vascular disorder characterized by thickening and hardening of the walls of the arteries. "HMGB1-modified cells preferably migrated to graft neointima and differentiated to CD31+ cells along with significant relief of transplant arteriosclerosis and inhibition of HMGB1 and RAGE expression in graft vessels." (PMID 29615103, 2018). "HMGB1 stimulated MSCs to migrate and differentiate to endothelial cells via RAGE signaling, which we translated to successful application in cell therapy for transplant arteriosclerosis." (PMID 29615103, 2018). "The current study aimed to evaluate whether the differentiation of MSCs to vascular cells would be influenced by high mobility group box 1 (HMGB1) and whether it could be used to provide favorable outcomes of MSC-based therapy for transplant arteriosclerosis." (PMID 29615103, 2018). "This may be caused by the lack of an increase of HMGB1 in surgical patients while MPO plasma release underlies a high number of influencing factors, such as arteriosclerosis as well as systemic heparin-application, which is highly prevalent in severely ill and cardiac surgical patients." (PMID 31936385, 2020).
calcification (3 papers, 2018 to 2021). Process by which organic tissue becomes hardened by the physiologic deposit of calcium salts. "Here, we used a 5/6 nephrectomized mouse model of CKD fed a high Pi diet to induce aortic calcification and examined the role of HMGB1 in VC associated with CKD." (PMID 29922171, 2018).
chronic asthma (3 papers, 2017 to 2022). An asthma that is characterized by the development of persistent airway inflammation and recurrent attacks of breathlessness and wheezing, which vary in severity and frequency. "Our previous study has shown that High-mobility group box protein 1 (HMGB1) is involved in the pathogenesis of airway remodeling using a mouse model of chronic asthma." (PMID 31247032, 2019). "In addition, HMGB1 expression is increased in the pulmonary epithelial cells in murine models of chronic asthma and acute lung injury, suggesting that these cells are the likely origins of the secreted HMGB1 in the BALF." (PMID 36741411, 2022). "More importantly, in a recent study we demonstrated that inhibition of HMGB1 activity decreased the levels of inflammatory mediators in the lung, whereas it could reverse airway remodeling in a allergen-induced murine model of chronic asthma." (PMID 31247032, 2019).
Chronic colitis (3 papers, 2014 to 2022). A chronic inflammatory disease of the large intestine (colon, cecum and rectum). "Translocation of the HMGB1 protein in myenteric neurons was associated directly with neuronal loss in chronic colitis." (PMID 36551259, 2022). "This suggests that HMGB1 is directly implicated in neuronal loss in chronic colitis." (PMID 36551259, 2022). "In this study, we utilize the Winnie mouse model of spontaneous chronic colitis and ex vivo culture models to elucidate the role of HMGB1 in enteric neuroinflammation." (PMID 36551259, 2022). "In response to oxidative stress and chronic colitis, myenteric neurons lost expression of HMGB1 in the nuclei and HMGB1 was translocated to the cytoplasm." (PMID 36551259, 2022). "Several studies have confirmed that EP is a potent inhibitor of HMGB1 and represents promising intervention in chronic colitis." (PMID 31303606, 2019). "Expression of HMGB1 was assessed in control mice and Winnie mice with chronic colitis." (PMID 36551259, 2022). "HMGB1 is important in regulating neuronal damage in the CNS, and its pathological activity is intertwined with oxidative stress and inflammation; both are evident in chronic colitis." (PMID 36551259, 2022). "In mice with chronic colitis, obvious variations in the expression pattern of HMGB1 were observed, with HMGB1 becoming translocated to the cytoplasm or absent in many neurons, which is characteristic of the secretory mechanism of HMGB1 in cells undergoing necroptosis." (PMID 36551259, 2022). "In this study, HMGB1 expression in the enteric nervous system and its relevance to intestinal neuroinflammation is explored in organotypic cultures of the myenteric plexus exposed to oxidative stimuli and in Winnie mice with spontaneous chronic colitis." (PMID 36551259, 2022). "The objective of this study was to develop HMGB1 specific DNA beads that could abrogate disease in murine models acute and chronic colitis, and thus have a potential as a therapy for human IBD." (PMID 25127031, 2014).
dysplasia (3 papers, 2009 to 2022). A usually neoplastic transformation of the cell, associated with altered architectural tissue patterns. "A total of 227 subjects were classified into 5 disease groups according to the 'gastritis-dysplasia-carcinoma' sequence of gastric carcinogenesis and their serum levels of HMGB1 were analyzed by an enzyme-linked immunosorbent assay (ELISA) method." (PMID 19476625, 2009). "Other studies have made similar observations in other tumors: In the carcinogenesis of gastric and cervical tumors, the expression level of HMGB1 has been found to be increased in the sequence of epithelial metaplasia-dysplasia-cancer." (PMID 35280439, 2022). "The aim of this study was to define the expression of HMGB1, key downstream proteins and lymphocyte phenotype in oesophageal neoplastic progression from BO to dysplasia to oesophageal adenocarcinoma in human tissue samples." (PMID 31831860, 2020). "Our data reveals that HMGB1 expression in background Barrett’s mucosa can predict the presence of dysplasia or cancer in histologically distinct mucosa, despite the dysplastic or carcinomatous epithelium being absent from the endoscopically sampled tissue." (PMID 31831860, 2020). "There was an increased intensity of nuclear HMGB1 in the background BO in those that had progressed to either dysplasia (71%) or cancer (67%) compared with BO from non-progressors (27%), p ≤ 0.017 and p = 0.024, respectively." (PMID 31831860, 2020). "This raises the potential for immunohistochemical detection of HMGB1 expression pattern to be used clinically in BO as a biomarker of likely focal progression even when biopsies do not include a focus of dysplasia or cancer." (PMID 31831860, 2020). "Cytoplasmic expression of HMGB1 was similar in background BO whether dysplasia was present or not." (PMID 31831860, 2020).
encephalomyelitis (3 papers, 2018 to 2021). Inflammation of the brain and the spinal cord. "Taken together, the results indicate that GL has a strong neuroprotective effect on EAE mice by reducing HMGB1 expression and release and thus can be used to treat central nervous system inflammatory diseases, such as MS." (PMID 30013568, 2018).
epidermolysis bullosa (3 papers, 2021 to 2022). Epidermolysis bullosa (EB) is a group of genetic skin diseases that cause the skin to blister very easily. "Moreover, HMGB1 levels are reported to be correlated to the Birmingham Epidermolysis Bullosa Severity score; this cytokine seems to be a promoter of skin carcinogenesis and to play a role in hindering the healing of skin wounds." (PMID 35207500, 2022). "Furthermore, HMGB1 serum levels were found to positively correlate with disease severity as captured by the Birmingham Epidermolysis Bullosa Severity Score and the EBDASI, which in turn are reported to increase with age." (PMID 34665781, 2021). "Meanwhile, the tissue distress factor, high-mobility group box-1 (HMGB1), Ccl27-Ccr10 chemotactic axis, and SDF-1α/CXCR4 signaling axis have been shown to promote the recruitment of endogenous MSCs to skin lesions, thus attenuating the pathology of epidermolysis bullosa." (PMID 33505474, 2021).
falciparum malaria (3 papers, 2006 to 2021). "As an inflammatory factor, HMGB1 was shown to be elevated in the serum of African children with falciparum malaria and was associated with severe complications, while HMGB1 levels gradually decreased during the recovery period." (PMID 33140586, 2021). "Since HMGB1 increases are associated with severity of falciparum malaria, this could account for the potentiating effects of platelets reported in an in vitro model of endothelial activation by P. falciparum." (PMID 17029647, 2006). "HMGB1 performed better as a prognostic indicator than the peripheral blood parasite count, a parameter commonly used as a prognostic indicator in falciparum malaria." (PMID 23506269, 2013). "HMGB1 has been shown to be increased, in proportion to degree of illness, in serum from African children infected with falciparum malaria." (PMID 17029647, 2006). "The role of HMGB1 in falciparum malaria remains to be further explored." (PMID 33140586, 2021). "In this study, HMGB1 levels at presentation were correlated with falciparum malaria disease severity in a cohort of paediatric patients, and there was a significant difference in admission HMGB1 levels between children who subsequently died from their infection versus those who survived." (PMID 23506269, 2013). "Cytokines such as TNF and IL-1, both increased in a wide range of systemic inflammatory diseases, including falciparum malaria, can induce a late-onset, but long-acting wave of a cytokine termed the high mobility group box 1 (HMGB1) protein, which prolongs and amplifies inflammation." (PMID 17029647, 2006).
Focal cortical dysplasia (3 papers, 2019 to 2024). A type of malformation of cortical development that primarily affects areas of neocortex. "Perhaps the elevation of inflammatory factors is related to the underlying disease itself, as previous literature has suggested that inflammatory factors such as IL-1β and HMGB1 are overexpressed in conditions like focal cortical dysplasia, medial temporal sclerosis." (PMID 39184857, 2024). "Increased expression of HMGB1 and TLR4 is seen in TLE and focal cortical dysplasia; HMGB1 can enhance both acute and chronic seizure susceptibilities in a TLR4-dependent manner." (PMID 31185666, 2019).
gastric tumor (3 papers, 2015 to 2023). "RAGE activation by HMGB1 enhanced invasion of gastric tumor cells (MKN45) in co-culture with M2-polarized THP1 macrophages and vice versa with M1 macrophages." (PMID 36686729, 2022). "Gefitinib, a common chemotherapeutic agent, activated autophagy and promoted the release of HMGB1, which was required to maintain gastric tumor cell survival." (PMID 25652880, 2015). "This demonstrated that HMGB1, particularly the cytoplasmic HMGB1, was rapidly released and accumulated in the culture media of the gefitinib-treated gastric tumor cells." (PMID 25652880, 2015). "Intriguingly, the interaction between HMGB1 and RAGE initiated signaling involving ERK1/2 phosphorylation and contributed to the cell proliferation in gastric tumor cells." (PMID 25652880, 2015). "As a regulator of cell death and survival, HMGB1 was released from the tumor cells undergoing gefitinib-induced autophagy, bound with RAGE and initiated signaling involving phosphorylation of ERK1/2, which contributed to gastric tumor cell proliferation." (PMID 25652880, 2015).
gastrointestinal stromal tumor (3 papers, 2015 to 2025). "Absence of HMGB1 staining mostly occurred in pheochromocytoma (90.0%), seminoma (72.4%), gastrointestinal stromal tumor (28.6%), adrenal cortical carcinoma (25.0%), and Hodgkin’s lymphoma (25.0%)." (PMID 40804938, 2025).
Gliosis (3 papers, 2019 to 2023). Gliosis is the focal proliferation of glial cells in the central nervous system. "Next, we evaluated the effects of long-term HMGB1 inhibitor treatment on APOE4-driven gliosis." (PMID 37863057, 2023). "Injection of HMGB1 into the hippocampus of young APOE4-tauopathy mice induced considerable and persistent gliosis." (PMID 37863057, 2023).